CRP (C-reactive protein)
Diseases named in the same sentence as CRP in open-access papers (continued):
Sharing a sentence is not in itself a finding about the gene and the disease.
cor pulmonale (11 papers, 2018 to 2025). Hypertrophy and dilation of the right ventricle of the heart that is caused by pulmonary hypertension. "NYHA class IV, type II respiratory failure, acid-base imbalance, and C- reactive protein may increase the risk of death in patients with cor pulmonale." (PMID 37400818, 2023). "In multivariate regression, RDW values were independently associated with pulmonary heart disease (OR = 1.371, 95% CI 1.197 to 1.571, p < 0.001) after correcting for white blood cell count, platelet count, mean platelet volume, platelet distribution width, and C-reactive protein." (PMID 36233510, 2022). "Among frequent AECOPD patients (n = 2179), those who have been prescribed TRQ (n = 505) had a significantly higher rate of cor pulmonale, cough, a larger amount of sputum, fever, and lower C-reactive protein (CRP) level on admission." (PMID 37056988, 2023). "outperformed assay-measured CRP as a marker of cardiopulmonary disease and long-term health status." (PMID 38692281, 2024). "When the regularization parameter λ reached its minimum value (λ_min = 0.00279), 11 key variables were selected: MLR, NLR, pulmonary heart disease (PHD), PLR, CRP, ELR, age, NT-proBNP, BLR, RDW, and SII." (PMID 40823588, 2025).
edema (11 papers, 2014 to 2023). An abnormal accumulation of fluid beneath the skin, or in one or more cavities of the body. "AT-FORGE score displays the combination of inflammatory burden (plasma fibrinogen and serum CRP), male sex, and peritumoral brain edema with the major diagnostic criteria of atypical meningioma." (PMID 34829359, 2021). "Analyses indicate that age (<3 years), enterovirus 71 (+), autonomic nervous system dysregulation, pulmonary edema/hemorrhage, C-reactive protein (CRP) (>40 mg/L), and cardiac troponin I (>0.04 ng/ml) are risk factors for fatality (all P < 0.05)." (PMID 32754560, 2020). "Conversely, there was no such relationship between C-reactive protein and the presence of oedema in CMR (p = 0.346)." (PMID 37109114, 2023). "Neither ESR nor CRP correlate with MR findings of vascular edema identified with electrocardiogram-gated edema-weighted MR." (PMID 24678735, 2014). "Mortality was higher among males, Tanzanians, those with oedema at baseline, those not ontuberculosis medication at baseline, and increased with age, with higher C-reactive protein(CRP), with lower CD4 cell count and with lower BMI at baseline (data presented by Wooddet al.)." (PMID 28393746, 2017). "Clipping may increase noncardiogenic pulmonary edema in the vasospasm period, resulting from the increased postoperative CRP level." (PMID 24818154, 2014).
endometritis (11 papers, 2011 to 2025). An acute or chronic, usually bacterial infectious process affecting the endometrium. "In the early postpartum period, ampicillin was continued in the standard endometritis prophylaxis protocol due to a high risk of systemic infection and elevation of C-reactive protein (CRP) levels." (PMID 41517265, 2025). "The third study was published in English and better defined endometritis as a temperature of 38.0 °C, excessive uterine tenderness or elevated C-reactive protein (±50 mg/l)." (PMID 26610697, 2015). "Hence, the high serum levels of TNF-α, interleukins, and CRP could introduce a logical alternative to diagnose clinical endometritis." (PMID 36930327, 2023). "The serum CRP levels increased by about 6 folds in SCE buffaloes than control that could be attributed to the promotion of mononuclear cells in response to uterine infection to produce their cytokines TNF-α and IL-8 which subsequently stimulated the emission of CRP from liver into blood stream." (PMID 32368278, 2020).
Ewing sarcoma (11 papers, 2013 to 2024). A small round cell tumor that lacks morphologic, immunohistochemical, and electron microscopic evidence of neuroectodermal differentiation. "Our findings showed that CRP was associated with the prognosis of children with Ewing’s sarcoma of the long bones." (PMID 36900365, 2023). "Our findings demonstrated that CRP was associated with the prognosis of children with Ewing’s sarcoma." (PMID 36900365, 2023). "We recommend pre-treatment measurement of the CRP in order to recognize children with Ewing’s sarcoma who are at greater risk of death or local recurrence." (PMID 36900365, 2023). "In addition, the tumor size and the response to chemotherapy were analyzed in patients treated surgically, confirming that pathological CRP was associated with poor survival in children with Ewing’s sarcoma." (PMID 36900365, 2023). "Recent studies examined the CRP–albumin ratio (CAR), showing that higher CAR levels were associated with poor prognosis in Ewing’s sarcoma." (PMID 39001318, 2024). "In order to investigate the predictive value of IPF%, we analyzed daily neutrophil, reticulocyte and thrombocyte count, the IPF%, the level of CRP and the presence of fever in samples from 11 patients treated for Ewing sarcoma." (PMID 36849723, 2023). "The purpose of the present study was to evaluate the prognostic role of C-reactive protein (CRP) in children with Ewing’s sarcoma." (PMID 36900365, 2023). "The purpose of the present study was to evaluate the prognostic role of CRP in children with Ewing’s sarcoma in relation to previously cited variables, including age, gender, tumor volume, tumor site, and chemotherapy-induced necrosis." (PMID 36900365, 2023). "In consideration of our findings, we can confirm the role of pretreatment CRP values in prognosis, local recurrence and of the presence of distant metastasis in patients with Ewing’s sarcoma." (PMID 36497377, 2022). "In our work, we analyze the role of LDH and CRP as prognostic factors in a population of pediatric and adolescent patients affected by Ewing sarcoma." (PMID 35804835, 2022). "After evaluating the statistical relevance of CRP values in correlation with prognosis, we can prudently confirm the involvement of this protein in the acute phase response in the Ewing sarcoma microenvironment." (PMID 36497377, 2022). "In Ewing’s sarcoma cases, we believe we can consider a CRP pre-treatment value of >0.5 mg/dL as a sensitive prognostic risk factor indication for distant metastasis and poor prognosis." (PMID 36497377, 2022). "The aim of this retrospective study was to analyse the role of C-reactive protein (CRP) as a prognostic factor for Ewing’s sarcomas." (PMID 36497377, 2022). "The relevance of CRP levels in Ewing sarcoma patients was already demonstrate in our 2022 study." (PMID 39001318, 2024). "Additionally, both CRMO and Ewing's sarcoma commonly present with elevated inflammatory markers, such as CRP and erythrocyte sedimentation rate, complicating differentiation based solely on imaging." (PMID 39429331, 2024). "The only studies that analyzed CRP in patients with Ewing’s sarcoma had important limitations." (PMID 36900365, 2023). "The purpose of the present study was to evaluate the prognostic role of CRP in children with Ewing’s sarcoma in relation to previously cited variables, including age, gender, tumor volume, tumor site, chemotherapy-induced necrosis, and other inflammatory biomarkers." (PMID 36900365, 2023). "Likewise, in 2013, a poorer DFS was statistically confirmed (p = 0.02) in patients with Ewing’s sarcoma and chondrosarcoma with an elevated CRP value." (PMID 36497377, 2022). "Recently, two other studies analyzed the possible association between pathological CRP and prognosis in patients with Ewing’s sarcoma, but the authors did not analyze tumor size, other inflammatory biomarkers, and did not consider the subgroup analysis of localized patients and metastatic patients." (PMID 36900365, 2023).
Ewing sarcoma (continued). "The correlation between the CRP level and a reduced DFS as well as poor prognosis in Ewing sarcomas showed a CC (Correlation Coefficient) of 0.51, with a p-value < 0.0005." (PMID 36497377, 2022). "Although no specific laboratory tests exist for Ewing sarcoma, some studies have correlated high CRP and LDH levels alongside other inflammatory markers with poor prognosis of the tumor." (PMID 39383765, 2024). "Our findings showed that pathological CRP was a negative prognostic factor for both survival and disease recurrence in children with Ewing’s sarcoma." (PMID 36900365, 2023). "A retrospective cohort study compared serial complete blood counts and the level of C-reactive protein (CRP) following induction chemotherapy for Ewing sarcoma and Non-Ewing sarcoma patients." (PMID 36849723, 2023). "Although pre-treatment serum CRP is a significant prognostic factor and a monitor of tumor aggressiveness in OS patients, it does not apply to Ewing's sarcoma and chondrosarcom." (PMID 24800842, 2014). "Similarly, a study in 2013 revealed statistically poorer disease-free survival (DFS) in patients with elevated CRP values, encompassing Ewing’s sarcoma and chondrosarcoma, without specifying cut-off values or entity distinctions." (PMID 39001318, 2024). "Our findings showed that CRP was a negative prognostic factor in children with Ewing’s sarcoma." (PMID 36900365, 2023). "However, the prognostic role of CRP in patients with Ewing’s sarcoma has not been evaluated." (PMID 36497377, 2022).
folate deficiency (11 papers, 2013 to 2025). A nutritional condition produced by a deficiency of FOLIC ACID in the diet. "Five selected determinants (iron, vitamin B12, and folate deficiency; low estimated glomerular filtration rate (eGFR); and high C-reactive protein (CRP)) were summed." (PMID 34372781, 2021). "Among the four vitamin deficiencies detected in this population, only folic acid deficiency was associated with higher CRP and only in lactating women." (PMID 28571565, 2017). "During lactation, folic acid deficiency was associated with higher CRP whereas parity, number of eosinophils and Mobiluncus score were associated with lower CRP." (PMID 28571565, 2017). "Second, although deficiencies of vitamins A, B12, D and folic acid were common, only folic acid deficiency was associated with higher CRP in lactating women." (PMID 28571565, 2017). "Folic acid deficiency was positively associated with CRP; the number of eosinophils, the Mobiluncus score and parity were negatively associated with CRP." (PMID 28571565, 2017). "Dysbiosis and inflammation are strongly related; the fourfold higher risk of folate deficiency of our individuals with increased CRP values is in line with the scientific evidence and suggests complex relationships between the nutritional status and the entire human ecosystem." (PMID 33026590, 2021). "We had previously shown that folic acid deficiency was positively associated with elevated CRP in lactating women in our population, which aligns with evidence that folic acid deficiency may promote increased BP probably as consequence of inflammation." (PMID 32292772, 2020). "Only folic acid deficiency during lactation was associated with higher CRP concentrations." (PMID 28571565, 2017). "Further, folic acid deficiency may play an under recognized role in leading to increased CRP concentrations in lactating women, in which case it might be recommended that folic acid supplementation be extended beyond 3 mo postpartum." (PMID 28571565, 2017). "Together, these results show that, after correcting for the normal elevation of CRP during pregnancy, the systemic CRP concentration is influenced by the mix of diverse infections, folic acid deficiency and maternal wood smoke exposure in this vulnerable population." (PMID 28571565, 2017). "The absence of a relationship between folic acid deficiency and CRP during pregnancy is most likely because women in our study were receiving folic acid supplementation during pregnancy." (PMID 28571565, 2017).
HCMV infection (11 papers, 2015 to 2025). "HCMV infection is positively correlated with the level of the inflammatory marker high-sensitivity C-reactive protein (hs-CRP) and low-grade inflammation, which increases the risk of ACS." (PMID 39941136, 2025). "In patients with active HCMV infection, i.e. group 1 and group 2, the mean concentrations of CRP, IL6, IL10 and MCP1 were found to be quite similar but significantly varied from group 3 patients." (PMID 35538132, 2022). "The objective of this study was to assess if HCMV infection affects four selected biomarkers of inflammation and endothelial function which are known predictors of cardiovascular morbidity and mortality: CRP, serum amyloid A (SAA), sVCAM-1, and sICAM-1." (PMID 32733818, 2020). "HCMV infection leads to increased CRP, which induces the expression of tissue factor in monocytes, initiates the coagulation process, and increases the risk of thrombosis; elevated CRP also enhances the coronary risk." (PMID 29409508, 2018). "In patients with EH specifically, CRP, TNF-α, NOX4, 8-OHDG, eNOS, and Ang II were associated with HCMV infection in all models (P<0.05)." (PMID 29752343, 2018). "A recent study revealed that CRP mediates the effects of apolipoprotein E on cytomegalovirus infection, demonstrating that CRP is a key suppressor of the relationship between the ε4 and the cytomegalovirus antibody levels." (PMID 25875811, 2015). "In addition to CRP, the proinflammatory cytokines TNF and interleukin-6 (IL-6) are secreted in response to HCMV infection and are independently associated with mortality due to CVD." (PMID 29752343, 2018). "Data concerning c reactive protein (CRP) and monokine induced by gamma interferon (MIG) are very limited and restricted to hCMV infection in transplant recipients." (PMID 36298700, 2022). "Another possibility is that that the single time point at which CRP was measured did not always overlap with viral shedding since the two studies were not designed to enroll participants with an active HCMV infection." (PMID 33500556, 2021).
hidradenitis suppurativa (11 papers, 2017 to 2025). A chronic suppurative and cicatricial disease of the apocrine glands occurring chiefly in the axillae in women and in the groin and anal regions in men. "For both PMC and ScienceDirect, ("Hidradenitis Suppurativa" OR "Acne Inversa") AND (adalimumab OR infliximab) AND ("C-reactive protein" OR "ESR"), the search strategy was used." (PMID 41458786, 2025). "The authors found that CRP levels and neutrophil count were correlated to a modified Hidradenitis Suppurativa score, suggesting that these laboratory markers are significant independent predictors for a more severe Hurley stage." (PMID 39407854, 2024). "Increasing CRP, ESR, NLR, PIV, and SII (P < .001) were significantly associated with increasing Hurley-stage and international hidradenitis suppurativa severity score system 4 (IHS4)-score in adjusted analysis." (PMID 38638915, 2024). "Moreover, a positive correlation was found between the serum concentration of S100A15 and CRP in patients with hidradenitis suppurativa, which may suggest an association between the disease and increased cardiovascular risk resulting from chronic systemic inflammation." (PMID 36235175, 2022). "The median CRP level in cases with hidradenitis suppurativa was 115 mg/L (range of 10–867 mg/L) and could be a potential marker of the disease, yet other authors discuss that CRP levels were only notably elevated in high inflammatory activity." (PMID 37873776, 2023). "The association between CRP and SAA was high in our population (rho = 0.755, p < 0.001), in accordance with other studies done in similar specific populations: patients with FMF, patients with hidradenitis suppurativa and patients with infectious diseases." (PMID 36434581, 2022). "Also, a comprehensive analysis by Gibson & Kimball (2021) commentary reveals a critical finding, as the article does not contain or discuss any data related to the serological inflammatory markers CRP or ESR in the context of adalimumab treatment for hidradenitis suppurativa." (PMID 41458786, 2025). "Clinical and patient-reported outcome measures included: the hidradenitis suppurativa-physician global assessment (HS-PGA = 4/severe), the numerical rating scale for pain (NRS-pain 7/10), the dermatology-life quality index (DLQI = 23), and C-reactive protein (CRP 4.8 mg/dl)." (PMID 32000436, 2020).
hyperandrogenism (11 papers, 2011 to 2025). Excessive secretion of androgens from the adrenal glands or gonads. "The presence of MUO was associated with highest hs-CRP levels (OR = 1.49, p < 0.001), more severe hyperandrogenism and cardio-metabolic indices (p < 0.001)." (PMID 34836180, 2021). "Also, T1D is a chronic inflammatory disorder that can be worsened by hyperandrogenism, contributing to increased ultrasensitive CRP concentrations." (PMID 40747135, 2025). "TNF-α can trigger hyperandrogenism and CRP is along with low-grade inflammation." (PMID 38778429, 2024).
Large vessel vasculitis (11 papers, 2017 to 2026). A type of vasculitis (inflammation of blood vessel walls) affecting large arteries such as the aorta and branches of the aorta. "The few reported cases of MDS-associated large vessel vasculitis presented in a similar manner to our patient: at an age >50 years, with acute inflammation, including tender vessels and a highly raised CRP, exceeding the median CRP of 52 mg/L in patients with temporal artery biopsy-proven GCA." (PMID 28298242, 2017). "Crucially, inflammatory markers including ESR and CRP were within normal limits, which is inconsistent with the active, systemic inflammation characteristic of large-vessel vasculitis or other highly inflammatory vasculitides such as polyarteritis nodosa." (PMID 41293154, 2025). "Laboratory findings showed an elevated C-reactive protein level and FDG-CT PET showed evidence of active large vessel vasculitis with diffuse abnormal artery uptake." (PMID 36851311, 2023). "TA remission is the absence of clinical signs and symptoms caused by active large vessel vasculitis and normalization of ESR and CRP." (PMID 35596814, 2022). "Notably, the patient’s positive ANA, elevated ESR and CRP, and recurrence of symptoms following physiotherapy raise the possibility of immune activation or subclinical vasculitic involvement, although definitive imaging for large-vessel vasculitis was not performed." (PMID 41258439, 2025). "In large-vessel vasculitis, given there are no specific monitoring tools, disease assessment is mostly based on clinical symptoms, conventional acute phase markers (erythrocyte sedimentation rate [ESR] and C-reactive protein [CRP]), and imaging." (PMID 32370776, 2020).